GAPDH (glyceraldehyde-3-phosphate dehydrogenase)
Diseases named in the same sentence as GAPDH in open-access papers (continued):
Sharing a sentence is not in itself a finding about the gene and the disease.
listeriosis (7 papers, 2014 to 2021). A bacterial infection caused by Listeria monocytogenes. "Further, dendritic vaccines loaded with peptides from virulence factors of LM such as lysteriolysin O (LLO) or glyceraldehyde-3-phosphate dehydrogenase (GAPDH) were effective for protection, but they are expensive measures to offer all pregnant women at risk of listeriosis." (PMID 28335280, 2016). "This inhibitory activity localized within the NAD binding domain of GAPDH at the N-terminal 1–22 peptides, also conferred listeriosis protection when used in dendritic cell-based vaccines." (PMID 33194812, 2020). "Taken together, these results indicate that LLO and GAPDH, as well as their epitopes, are good candidates to include in cellular vaccine designs against listeriosis." (PMID 24600592, 2014). "This is believed to be the first study to explore the use of a novel GAPDH antigen as a potential DC-based vaccine candidate for listeriosis, whose efficiency appears to highlight the relevance of vaccine designs containing multiple CD4+ and CD8+ epitopes." (PMID 24600592, 2014). "To examine whether DCs loaded with LLO or GAPDH epitopes might also confer protection against listeriosis, we prepared DC vaccines loaded with peptides, DC-LLO91−99, DC-LLO189−201 or DC-GAPDH1−22, and compared them for protection with DCs loaded with an L. monocytogenes lysate (DC-LM lysate)." (PMID 24600592, 2014). "In this study, we examined the ability of a novel GAPDH peptide, GAPDH1−22 to confer protection against listeriosis when incorporated into macrophages or DCs as vaccine vectors." (PMID 24600592, 2014). "LLO91–99 and glyceraldehyde-3-phosphate dehydrogenase (GAPDH), GAPDH peptide 1–22 (GAPDH1–22) and GAPDH1–15 were used with success in DC vaccines for listeriosis as they induce strong cytotoxic-T-cell responses and DC activation, which are both useful properties for cancer vaccines." (PMID 26942874, 2016). "As a first approach using cellular vaccine vectors against listeriosis, we prepared different BMDM and DC vaccine vectors containing LM-WT, LLO, or GAPDH, and used them in vaccination protocols against an L. monocytogenes challenge of 5 × 103 bacteria/mice (n = 5), inoculated for 3 days." (PMID 24600592, 2014).
renal carcinoma (7 papers, 2008 to 2024). A carcinoma arising from the epithelium of the renal parenchyma or the renal pelvis. "The high expression of GAPDH, PSAT1, PGLS, and LDHC indicated a short DFS and a high risk of developing renal cancer." (PMID 33564363, 2021). "Small RNA-induced knockdown of GAPDH in renal carcinoma cells was accompanied by increased expression of IFI6, OAS3, and UBE2L6." (PMID 30253781, 2018). "We verified the expression of G6PD and GAPDH in distinct renal cancer cell lines." (PMID 39034372, 2024). "In brief, KCNAB2 and GAPDH could act as candidate biomarkers to identify patients suffering from renal cancer and even early renal cancer." (PMID 36789694, 2022). "Interestingly, it was reported that GAPDH is commonly upregulated in various cancers (e.g., renal cancer)." (PMID 36789694, 2022). "A significant correlation was found between XIAP expression levels (ratio to actin, GAPDH) and the sensitivity to A4 (IC50, μM) in breast, ovary and kidney carcinomas." (PMID 32587235, 2020). "The research revealed no statistically significant variations in GAPDH expression, the Ct value of LncRNA was significantly lower in renal cancer tissues than in normal renal tissues, suggesting that LncRNA expression was upregulated in renal cancer." (PMID 35719925, 2022).
type 2 diabetes (7 papers, 2012 to 2023). "Furthermore, higher levels of GAPDH may also contribute to the loss of glucose and lipid homeostasis and to the eventual development of type 2 diabetes." (PMID 25180703, 2014). "In mouse models of type 2 diabetes, GAPDH was shown to be hypermalonylated, which includes increased malonylation of K2136." (PMID 30659183, 2019). "GALNT2 mRNA levels, as normalized for GAPDH expression, were progressively reduced from non-obese non-diabetic individuals, to obese non-diabetic individuals and to obese patients with type 2 diabetes (p for trend <0.001)." (PMID 23894607, 2013).
astrocytoma (6 papers, 2007 to 2022). "The geNorm analysis clearly showed that GAPDH was highly consistent in their expression levels across 40 astrocytoma tissue samples and 20 NAT samples in the training set." (PMID 26252651, 2015).
pancreatic adenocarcinoma (6 papers, 2014 to 2024). "The loss of UCP2 in different human pancreatic adenocarcinoma cell lines further stimulated autophagy through the ROS-dependent nuclear translocation of glyceraldehyde-3-phosphate dehydrogenase (GAPDH)." (PMID 36499405, 2022). "UCP2 inhibitor genipin can suppress growth of pancreatic adenocarcinoma cells and trigger cell apoptosis via promoting GAPDH nuclear translocation." (PMID 38217303, 2024). "In this study, we demonstrate that the 3-bromo-isoxazoline derivative AXP-3019 is able to inhibit the glycolytic enzyme GAPDH resulting in inhibition of cell proliferation and blockage of tumour-mass growth in a mouse model of human pancreatic adenocarcinoma." (PMID 35804925, 2022). "Remarkably, levels of glyceraldehyde-3-phosphate dehydrogenase (GAPDH) were found elevated in human pancreatic adenocarcinomas compared to normal pancreas, as well as in several other cancer tissues." (PMID 35804925, 2022). "In pancreatic adenocarcinoma cells, the combination treatment of Everolimus, an antitumor agent that inhibits the mTOR pathway, with Genipin synergistically inhibited cancer cell proliferation by increasing the nuclear translocation of GAPDH." (PMID 36499405, 2022). "As a positive control, we included the pancreatic adenocarcinoma cell line HPAF-II (blood group A Se/Se), which showed high levels of ABO transcripts comparable to control gene GAPDH." (PMID 24454787, 2014). "In pancreatic adenocarcinoma cells, genipin or UCP2 siRNA repressed cell proliferation, induced nuclear translocation of the glycolytic enzyme glyceraldehyde-3-phosphate dehydrogenase (GAPDH), and increased the expression of the autophagic marker LC3-II and autophagosomes." (PMID 35628447, 2022).
Stroke (6 papers, 2012 to 2019). Sudden impairment of blood flow to a part of the brain due to occlusion or rupture of an artery to the brain. "For example, the antiphospholipid (aPL) autoantibodies are related to stroke and transverse myelitis, the anti-ribosomal P antibodies are specifically associated with psychosis, and anti-GAPDH is reported to be associated with cognitive dysfunction." (PMID 31049359, 2019). "We have also found that aggregates of GAPDH form abundantly after middle cerebral artery occlusion in a mouse stroke model in which oxidative stress is responsible for neuronal cell death (in preparation)." (PMID 28167533, 2017). "In stroke models, nuclear GAPDH cascades are triggered leading to posttranscriptional modifications and allowing GAPDH to play a crucial role in brain damage." (PMID 27618915, 2016).
systemic lupus erythematosus (6 papers, 2013 to 2025). An autoimmune multi-organ disease typically associated with vasculopathy and autoantibody production. "The higher amount of lysosomal GAPDH observed in the lupus mice group is also suggestive of its enhanced delivery to this compartment for degradation, and consequently of increased CMA activity." (PMID 33092174, 2020). "Anti-GAPDH autoantibodies were positively correlated with SLEDAI-2K, ESR, IgG, and IgM, which suggested that anti-GAPDH could work as an indicator of lupus disease activity." (PMID 31049359, 2019). "One other plausible explanation for the differences between the in vivo situation and isolate lysosomes could be that only the CMA of specific substrates is accelerated in the lupus context and that substrates such as Tau or GAPDH are not among those." (PMID 33092174, 2020).
atherosclerosis (5 papers, 2016 to 2024). A disease characterized by the build-up of fatty material and calcium deposition in the arterial wall resulting in partial or complete occlusion of the arterial lumen. "Potential targets such as GAPDH, AKT1, TNF, IL6, and SRC were implicated in key pathways including MAPK signaling pathway, lipid and atherosclerosis, PI3K-Akt signaling pathway, and IL-17 signaling pathway." (PMID 39822742, 2024). "We hypothesise that in older TAV patients with dilated aortas, atherosclerosis and tissue hypoxia may be more prevalent which may explain why GAPDH becomes less stable in these groups." (PMID 27727313, 2016). "To explore the functions of TNK1 in atherosclerosis, we detected the expression of TNK1 in different cell lines, using GAPDH as reference." (PMID 32694928, 2020).
breast tumor (5 papers, 2010 to 2022). "In this context, we saw a decrease in GAPDH protein levels, which has been associated with a lower glycolytic rate and a decrease in breast tumor proliferation." (PMID 36359862, 2022). "Following normalization of RCC2 expression to GAPDH expression, there was a significant increase in RCC2 expression in these ER + breast tumor tissues compared with that in breast fibroadenoma tissues (p=0.004)." (PMID 32565805, 2020). "The expression of six HKs (TFRC, GUSB, GAPDH, ACTB, HPRT1 and RPLP0) was investigated using geNorm and NormFinder softwares in forty breast tumor, four normal and eight adjacent tissues." (PMID 21702980, 2011). "The first dataset includes relative expression levels of 6 reference genes (ACTB, GAPDH, MRPL19, PSMC4, PUM1, and SF3A1) quantified in 80 breast tumor samples." (PMID 20470420, 2010).
colorectal tumor (5 papers, 2010 to 2024). "COX-2 mRNA levels, normalized with respect to tissue weight or mRNA levels of the housekeeping genes B2M or GAPDH, were over-expressed in 80%, 70% and 40% of the colorectal tumor tissues, as compared to the paired adjacent normal colorectal mucosa samples, respectively." (PMID 24383454, 2014). "Proteins that regulate glycolysis (PGK1, PGAM1, ENO1, PKM, TKT), ammonia detoxification (GLUD1), and other metabolic pathways (LDHA, GAPDH, MDH2) were reported to be differentially expressed in mouse xenograft colorectal tumor models with different radio- responsiveness." (PMID 38410100, 2024).
heart failure (5 papers, 2013 to 2025). Inability of the heart to pump blood at an adequate rate to meet tissue metabolic requirements. "The results showed that the expression levels of HIF-1α, IL10, PAD4, ACTG1, SOD2, and GAPDH were higher in heart failure patients with Qi deficiency and blood stasis syndrome compared to the HP group." (PMID 40671145, 2025). "NAD+ was essential for ATP production around lysosomes and the GAPDH/PGK1 complex was associated with lysosomes, suggesting that reduced NAD+ due to mitochondrial translation deficiency is an important cause of heart failure." (PMID 33528041, 2021). "Heart failure was also associated with promoter hypomethylation of enriched glycolytic pathways and anaerobic metabolic processes, including phosphofructokinase (PFKL and PFKP), enolase (ENO1, ENO2, and ENO3), and glyceraldehyde-3-phosphate dehydrogenase (GAPDH)." (PMID 37893188, 2023). "Despite this, some findings suggest that GAPDH possesses high expression stability in heart failure and normal heart conditions." (PMID 39146015, 2024).
influenza (5 papers, 2011 to 2025). An acute viral infection of the respiratory tract, occurring in isolated cases, in epidemics, or in pandemics; it is caused by serologically different strains of viruses (influenzaviruses) designated A, B, and C, has a 3-day incubation period, and usually lasts for 3 to 10 days. "They bind to host factors, such as GAPDH, which facilitate bacterial colonisation, especially in the respiratory epithelium during co-infections with influenza." (PMID 40005491, 2025). "Host GAPDH on surface of dying lung epithelial cells was found to interact with Strepococcus pneumoniae resulting in secondary infection following influenza infection." (PMID 34593755, 2021). "While most research has focused on andrographolide itself, the findings of this study suggest that flavonoid components such as Mono‐O‐methylwightin and Andrographin also possess strong anti‐influenza potential, especially through high‐affinity interactions with the core target GAPDH." (PMID 41439108, 2025). "A. paniculata may exert its therapeutic effects against influenza by modulating core targets such as TNF, IL‐6, AKT1, GAPDH, and STAT3." (PMID 41439108, 2025). "A. paniculata may exert therapeutic effects against influenza by acting on core targets, such as TNF, IL‐6, AKT1, GAPDH, and STAT3." (PMID 41439108, 2025).
liver fibrosis (5 papers, 2012 to 2022). "Because advanced PSC causes liver fibrosis and can result in extensive loss of parenchyma, we standardized β-catenin expression to the expression of housekeeping gene GAPDH for accurate comparison." (PMID 34997170, 2022). "The ratio of α-SMA/GAPDH in liver fibrosis model group was higher than that in control group, with 200 mg/μl insulin containing Snail-treated for 96 h, ratio of α-SMA increased significantly in liver fibrosis model group than control group." (PMID 23226767, 2012). "Along with the progression of liver fibrosis, IGHV, GAPDH, C1s, GRP78 and V-ATPase levels significantly increased, and PPBP, CD9, Lp(a) and SAP levels significantly decreased." (PMID 35797333, 2022).
myocardial infarction (5 papers, 2011 to 2024). Gross necrosis of the myocardium, as a result of interruption of the blood supply to the area, as in coronary thrombosis. "We evaluated human GAPDH expression at 3 different parts from the infarction area and identified implanted cells in the mouse tissue 6 weeks after myocardial infarction following hMSC application with selective binding human nuclei antibody (HNA)." (PMID 21347366, 2011). "GAPDH, GNAS, and ACTB were shown to be the most stable genes in platelets of healthy individuals, while HDGF, GNAS, and ACTB were the most stable in platelets of patients with the history of myocardial infarction." (PMID 23389042, 2013). "We found GAPDH, GNAS, and ACTB to be the best combination of reference genes for platelet transcript level studies in healthy individuals, while HDGF, GNAS, and ACTB are the best for studies in patients with the history of myocardial infarction." (PMID 23389042, 2013). "Our results indicate that GAPDH, GNAS, and ACTB are the most stable genes expressed in platelets of healthy individuals and HDGF, GNAS, and ACTB were identified as the most stable reference genes expressed in platelets from patients with the history of myocardial infarction." (PMID 23389042, 2013).
oral cancer (5 papers, 2011 to 2025). "This analysis revealed that in addition to the positive control GAPDH, all oral cancers (except SCC4) upregulated the miR-155 downstream targets OLFML3, TBR1, BACH1, ZNF652, IRF2-BP2, and ZIC3." (PMID 38396844, 2024). "This analysis revealed that in addition to the positive control GAPDH, all oral cancers upregulated the miR-145 downstream targets MBTD1 and FSCN1." (PMID 38396844, 2024). "By targeting both AKT1 and GAPDH, Nyctanthic acid may offer a more comprehensive therapeutic approach, potentially improving outcomes in oral cancer where resistance and recurrence remain major clinical challenges." (PMID 40933552, 2025). "Control gene (GAPDH) levels varied among patient samples, but the ratiometric analysis of Nup62 or Nup88 with GAPDH indicates that both Nups are significantly overexpressed in oral cancer tissues (n=4)." (PMID 36845732, 2023). "Screening data confirmed the production of structural (beta actin) and metabolic (GAPDH) mRNA in all cell lines, as well as the presence of miR-365 among the oral cancer cells (SCC9, SCC15, SCC25, and CAL27) but not the normal OKF4 cell line." (PMID 32727045, 2020).
pancreatic ductal adenocarcinoma (5 papers, 2013 to 2024). An infiltrating adenocarcinoma that arises from the epithelial cells of the pancreas. "Nuclear localization of GAPDH can be modulated by cellular signaling cascades, including phosphoinositide 3-kinase (PI3K) and AMPK signaling pathways, in HDFs and in pancreatic ductal adenocarcinoma." (PMID 35020602, 2022). "PRMT4 has also been shown to suppress glutamine metabolism in pancreatic ductal adenocarcinoma by methylating malate dehydrogenase 1 (MDH1), or inhibits HCC glycolysis by methylating glyceraldehyde-3-phosphate dehydrogenase, both leading to reduced growth and proliferation of cancer cells." (PMID 36823188, 2023). "The expression of Six1 mRNA in pancreatic ductal adenocarcinomas samples was significantly higher than in the adjacent non-tumor pancreatic tissues after normalization using GAPDH (P<0.01)." (PMID 23527134, 2013).
periodontitis (5 papers, 2016 to 2025). An acute or chronic inflammatory process that affects the tissues that surround and support the teeth. "An elongation factor-encoding gene was most prevalent in peri-implantitis and periodontitis (9.89 ± 1.07% and 10.13 ± 2.26%, respectively), followed by glyceraldehyde 3-phosphate dehydrogenase, alkyl hydroperoxide reductase (ahpC), and enolase genes." (PMID 27499042, 2016). "In real-time polymerase chain reaction (PCR) analysis, the relative expression of HO-1 per glyceraldehyde-3-phosphate dehydrogenase (GAPDH) in the periodontitis group was 1.7 times higher than that of the control group." (PMID 27854327, 2016). "Also, significant differences were observed with genes involved in carbohydrate metabolism, where glyceraldehyde-3-phosphate dehydrogenase was significantly higher expressed in periodontitis, as compared to fructose bisphosphate aldolase, which was significantly less expressed." (PMID 34556654, 2021).
prostate tumour (5 papers, 2007 to 2017). "Immunostaining of prostate tumour sections demonstrated expression of glyceraldehyde-3-phosphate dehydrogenase (GAPDH), recoverin, alpha-enolase and synaptophysin in NET cells." (PMID 28382556, 2017). "ACTB and GAPDH were chosen as they were already used for CLDN gene expression analyses in canine prostate tumour and mammary tissue and tumour derived cell lines." (PMID 27690019, 2016). "When normalised to GAPDH, PKCα protein expression varied considerably between the five cell lines, being weakest in P4E6 cells derived from an early prostate tumour." (PMID 21266973, 2011). "β-actin was used for normalization rather than GAPDH because GAPDH expression levels have been shown to correlate with pathologic stage in human prostate tumors." (PMID 17376245, 2007).
brain tumor (4 papers, 2007 to 2018). "In each individual experiment using individual housekeeping genes, CNS-NB samples showed significantly elevated PLK4 expression levels when compared to non-embryonal brain tumors (LGG) (GAPDH p = 0.0016; HPRT1 p < 0.0001; HMBS p = 0.0116)." (PMID 30400339, 2018).
Cognitive impairment (4 papers, 2017 to 2024). Abnormal cognition is characterized by deficits in thinking, reasoning, or remembering. "In both models of AD, animals with elevated levels of GAPDH in the hippocampus demonstrated significant cognitive impairment." (PMID 34341704, 2021). "As a classical glycolytic enzyme, GAPDH was validated by ELISA as being significantly downregulated in the TBI patients with cognitive impairment." (PMID 28251161, 2017). "Interestingly, our results revealed that AD signaling pathways (including LPL, GAPDH, and CaM) might play an important role in the pathophysiology of post-TBI cognitive impairments." (PMID 28251161, 2017).
dementia (4 papers, 2020 to 2023). Loss of intellectual abilities interfering with an individual's social and occupational functions. "Pharmacologically, several anti-dementia drugs, such as tacrine, donepezil, and deprenyl, are administered to target the GAPDH apoptotic cascade process for treating dementia." (PMID 36450447, 2023).